MGMT (O-6-methylguanine-DNA methyltransferase)
Diseases named in the same sentence as MGMT in open-access papers (continued):
Sharing a sentence is not in itself a finding about the gene and the disease.
glioma (continued). "Besides, the presence of O6-methylguanine-DNA methyltransferase (MGMT) promoter methylation predicts benefit from temozolomide-based chemotherapy in patients with IDH-wildtype glioma." (PMID 34858984, 2021). "In addition, several molecular mechanisms affecting signaling pathways contributing to the expression and activation of MGMT are highly responsible for the poor outcomes of TMZ-resistant glioma patients." (PMID 34202078, 2021). "RIP2 was observed to induce upregulation of MGMT expression in glioma cells." (PMID 33460245, 2021). "MGMT removed O6-MG from DNA, protect tumor cells from the damage of alkylating agents, and then lead to temozolomide resistance of tumor cells, which has become an important factor restricting the effect of glioma chemotherapy." (PMID 34557405, 2021). "AEBP1 was overexpressed in MGMT promoter unmethylation type glioma which might be an important factor in predicting TMZ sensitivity." (PMID 34373835, 2021). "Moreover, O6-methylguanine–DNA methyltransferase (MGMT) promoter methylation in gliomas indicates benefits from temozolomide treatment." (PMID 34211979, 2021). "Furthermore, IDH mutations correlated with low Ki-67 protein expression (<15%, P = 0.011), and MGMT methylation was more frequently detected in frontally located gliomas (P = 0.022)." (PMID 34159191, 2021). "A study elucidated a potential mechanism for glioma recurrence in which normal glioma-associated astrocytes protected MGMT negative glioma cells from temozolomide (TMZ)-induced apoptosis by transferring EVs MGMT mRNA." (PMID 33670924, 2021). "After all, our findings bring the new insight that STAT1 may repress glioma carcinogenesis by modulating MGMT expression." (PMID 34544433, 2021). "Moreover, MGMT methylation was enriched in IDH-mutant/TERTp-mutant gliomas, and Ki-67 protein expression was the highest in the IDH-wild type/TERTp-mutant group." (PMID 34159191, 2021). "Similarly, MGMT promoter methylation and TERT promoter mutations, both well-known molecular markers correlated to drug-resistance in gliomas, were also found to be preserved in GBM primary cells but lost in grade II/III primary cells." (PMID 33981597, 2021). "Therefore, we confirmed the methylation status of the MGMT promoter in TMZ-resistant glioma cells treated with curcumol and/or TMZ using MS-PCR." (PMID 34739394, 2021). "Other studies with different approaches, defined the potential use of radiomics on FET-PET imaging to differentiate MS from glioma II°–IV° or on 18F-DOPA-PET to predict pathologic Methylation of the O6-methylguanine methyltransferase (MGMT) gene promoter status in gliomas." (PMID 34940083, 2021). "Molecular markers of DNA methylation for the early diagnosis and prognosis prediction of tumors and tumor-targeting drugs based on epigenetics have been widely studied, for example, the application of O-6-methylguanine-DNA methyltransferase (MGMT) DNA methylation in molecular diagnosis of glioma." (PMID 34434284, 2021). "In a retrospective study of EORTC-22033 randomized phase III trial samples, MGMT promoter methylation was revealed to have predictive value in IDH-mutant grade II glioma treated with TMZ, but the cutoff value used in that study was dramatically higher than that commonly used in IDH-wildtype GBM30." (PMID 33628600, 2021).
glioma (continued). "In addition to the ER stress risk score, there are numerous known prognostic factors for glioma, such as age, gender, WHO grade, IDH mutation status, 1p19q codeletion status and MGMT promoter methylation status." (PMID 33611848, 2021). "Besides, the presence of O6-methylguanine-DNA methyltransferase (MGMT) promoter methylation is predictive of response to temozolomide-based chemotherapy in patients with IDH-wild-type glioma." (PMID 34805164, 2021). "However, recent studies show that even MGMT hypermethylated glioma cells show robust expression of MGMT through promoter-independent mechanisms, thereby developing resistance to TMZ treatment." (PMID 33668200, 2021). "The higher risk score was also detected in glioma samples with the molecular features of MGMT promoter unmethylated or 1p/19q non-codeleted, which were generally thought to play a key role in the progression of glioma." (PMID 34307339, 2021). "MGMT promoter methylation was more frequent in gliomas with H3K27me3 loss, but statistical significance was not reached." (PMID 34165590, 2021). "Other studies showed the proapoptotic role of β-catenin in the reduction of resistance to TMZ by cordycepin on glioma cells, by inhibiting O6-methylguanine-DNA methyltransferase (MGMT), as well as by depleting glutathione (GSH) and generating reactive oxygen species (ROS)." (PMID 34577571, 2021). "In grade III and IV gliomas, the frequency of MGMT methylation (53% and 34%, 90respectively) and IDH mutations (88% and 32%, respectively) reported in our study was similar to the previously reported incidence of biomarkers in high-grade gliomas." (PMID 34055639, 2021). "Epigenetic modification is the most common determinant of inactivation of MGMT in glioma." (PMID 34544433, 2021). "Next, other common glioma biomarkers, such as MGMT status, 1q/19q codeletion and ATRX loss, were not included in the analysis of the signature." (PMID 33828990, 2021). "Additionally, DDX60 favored its expression in mesenchymal and classical subtype, MGMT unmethylated (P < 0.001), ATRX wild-type (P < 0.001), TERT promoter mutated (P < 0.001), and IDH wild-type gliomas (P < 0.001)." (PMID 34178649, 2021). "Benefitting from the recognition of glioma biomarkers such as O6-methylguananine–DNA methyltransferase (MGMT) and epidermal growth factor receptor, patients with glioma have been diagnosed as early as possible, but the overall 5-year survival rate is still far from satisfaction." (PMID 33414423, 2021). "These molecular epidemiological results provide logical evidence to support the contention that STAT1 may mediate its tumor suppressor function in glioma by regulating MGMT expression." (PMID 34544433, 2021). "Notably, previous study demonstrated that methylation modification of MGMT promoter can lead to increased chemotherapeutic effect in high grade gliomas." (PMID 33718217, 2021). "The most relevant biomarker for glioma is MGMT promoter methylation status." (PMID 33919036, 2021). "A recent study revealed that XIST enhanced glioma cell chemoresistance to temozolomide via regulating miR-29c/SP1/MGMT axis, which could be a novel target for glioma treatment." (PMID 34930117, 2021). "The results indicated that inhibition of NF‐κB or MGMT could enhance the sensitivity of glioma cells to TMZ." (PMID 33460245, 2021). "No information is available on the initiation and elongation of the MGMT transcripts in human cells and whether these events are altered in glioma to promote an active transcription or its attenuation." (PMID 34201219, 2021). "Besides, MGMT promoter methylation was an independent prognostic biomarker of glioma sensitive to temozolomide and radiotherapy." (PMID 33542188, 2021). "Therefore, MGMT promoter methylation is a robust indicator of glioma patients’ sensitivity to TMZ treatment." (PMID 34422648, 2021).
glioma (continued). "Good interactions at the active pocket and binding affinity of AC26 with efflux pumps and MGMT might be responsible for synergistic effect against resistant Glioma cells in combination with TMZ." (PMID 33791212, 2021). "Moreover, we believed that genes associated with histological grades, IDH mutation, MGMT methylation and EMP3 expression in glioma were also potential prognostic factors for glioma." (PMID 34335936, 2021). "Furthermore, to quantitatively predict the prognosis of glioma patients, we constructed a nomogram using grade, IDH mutation status, MGMT promoter methylation status, 1p19q codeletion status and PLOD1 expression level." (PMID 34040895, 2021). "Since IDH mutation, MGMT methylation, and 1p19q codeletion indicated high malignancies and poor prognosis, the expression of CD74 might be associated with glioma malignancies." (PMID 34540893, 2021). "This work also illustrates that temozolomide (TMZ) use in unmethylated MGMT lower-grade gliomas may benefit the OS after tumor recurrence." (PMID 33392065, 2020). "In glioma, mutations and epigenetic changes such as isocitrate dehydrogenase (IDH) mutations, chromosome 1p/19q co-deletion, and O6-methylguanine–DNA methyltransferase (MGMT) hypermethylation have demonstrated clinical importance." (PMID 32355162, 2020). "MGMT promoter methylation status and IDH mutations are important prognostic biomarkers for gliomas." (PMID 32513276, 2020). "Furthermore, ultrasonic samples taken from different parts of the glioma showed heterogeneity in the methylation status of the O6-methylguanine DNA methyltransferase (MGMT) gene promoter and cellular proliferation indices." (PMID 32226940, 2020). "It therefore remains to be shown in future studies whether MGMT promotor methylation indicates that the use of chemotherapy translates into improved outcome in glioma WHO grade II." (PMID 33184319, 2020). "Isocitrate dehydrogenase (IDH) mutations, codeletion of chromosomal arms of 1p and 19q, O6-methylguanine-DNA methyltransferase (MGMT) promoter gene methylation, and histone protein H3.3 or H3.1lys27Met mutations (H3K27M) represent prevalent subtypes in the population with glioma." (PMID 32964017, 2020). "However, the treatment of gliomas cannot be processed by genotype alone since IDH mutation or 1/19q codeletion status tends to be used for classifying grades II and III and MGMT promoter methylation for grade IV." (PMID 33746649, 2020). "Furthermore, significant differences between MGMT promotor methylated and unmethylated gliomas were identified for ADCmin, being increased in unmethylated gliomas." (PMID 32158691, 2020). "On the contrary, IDH2 mutational pattern and MGMT methylation status showed comparable frequency in both methylated and unmethylated MGMT gene for same series of glioma patients and therefore, did not correlate significantly (p > 0.05)." (PMID 33552543, 2020). "In this study, MGMT methylation was mostly seen in glioma grade II." (PMID 33247700, 2020). "In summary, here we have presented MGMT genomic rearrangements not only as a novel mechanism of resistance to TMZ in a subset of gliomas but also, to our knowledge, as a unique genetic alteration never described before in response to other chemotherapeutic agents." (PMID 32753598, 2020). "In addition, TERT promoter mutation seems to be a useful biomarker in clinically evaluating sensitivity to TMZ for treatment of glioma patients who carry MGMT methylated status." (PMID 32957941, 2020). "Interestingly, we found that in IDH-wild-type glioma patients, high MGMT expression indicates worse survival (P = 0.02, log-rank test), while it is associated to a trend of better survival in IDH-mutant patients (P = 0.04, log-rank test)." (PMID 32753598, 2020).
glioma (continued). "In recent years, significant success has been achieved in the use of biomarkers in the diagnosis of central nervous system (CNS) tumors, which are already used in everyday medical practice, such as methylation in promoter O6-methylguanine-DNA-methyltransferase (MGMT) gene in gliomas." (PMID 33023145, 2020). "The methylation status of MGMT, rather than the protein expression itself, has been one predictor of alkylating drugs susceptibility and long-term survival in glioma patients." (PMID 33282092, 2020). "Understanding the biological role of MGMT promotor status in glioma WHO grade II may be useful in future management of such patients." (PMID 33184319, 2020). "Moreover, the results showed that glioma-related mutant genes included MGMT (n = 14), IDH1 (n = 8), IDH2 (n = 1), 1p/19q (n = 3), and BRAF (n = 2)." (PMID 32973641, 2020). "Gliomas evade current therapies through primary and acquired resistance and the effect of temozolomide is mainly restricted to methylguanin‐O6-methyltransferase promoter (MGMT) promoter hypermethylated tumors." (PMID 32991787, 2020). "However, as the present study indicates, the OS of sGBM is better by using TMZ in previous lower-grade tumors, even in unmethylated MGMT glioma patients." (PMID 33392065, 2020). "In our study, glioma with IDH1 mutation showed a higher MGMT promoter methylation compared to glioma without this mutation (55.6% vs. 18%, p=0.032)." (PMID 32856857, 2020). "In addition, glioma cells in 3D scaffold exhibited enhance chemotherapeutic resistance and expression of O6-methylguanine DNA methyltransferase (MGMT) compared to the cells grew in 2D culture." (PMID 35519701, 2020). "Although several biomarkers such as MGMT, STAT3, and APNG have been explored to be associated with the sensitivity of TMZ, TMZ resistance in gliomas is still incompletely elaborated." (PMID 33362537, 2020). "Additionally, the methylation level of the MGMT promoter region has been widely used as a predictor of chemotherapeutic drug sensitivity in gliomas." (PMID 33230136, 2020). "Here we screened 99 different malignancy grade astrocytomas for CASC2, and miR-21 gene expression by real-time quantitative polymerase chain reaction (RT-qPCR) in isocitrate dehydrogenase 1 (IDH1) and O-6-methylguanine methyltransferase (MGMT) assessed gliomas." (PMID 33120918, 2020). "A total of 94 gliomas had known MGMT promoter methylation status (45 methylated, 49 unmethylated)." (PMID 32051040, 2020). "It is a resistance mechanism of TMZ in MGMT-positive patients that causes paraventricular recurrence, and previous research reported that the microenvironment of TMZ resistance is related to the migration of glioma cells." (PMID 33585189, 2020). "Likewise, methylation of the O6-methylguanine-DNA methyltransferase (MGMT) promoter has prognostic significance in patients, which occurs in approximately 50% of gliomas, and definitely more often in GBM recurrence." (PMID 32977537, 2020). "It is less well-defined whether MGMT promotor status also adds prognostic information in glioma WHO grade II." (PMID 33184319, 2020). "The risk signature was correlated with glioma grade, age, IDH, and MGMT promoter status." (PMID 31681595, 2019).
glioma (continued). "In addition, ITSS grades of MGMT-methylated gliomas were lower than those of MGMT-unmethylated gliomas (p = 0.041)." (PMID 31745161, 2019). "We developed a pyrosequencing-based method because it is well established on FFPE material, allows a low level variant detection and is frequently used in diagnostic pathology services for other types of somatic methylation analysis (e.g. MGMT promoter methylation analysis in glioma)." (PMID 31308404, 2019). "Moreover, the results showed that high expression of TMEM71 was highly enriched in the IDH‐wild‐type, MGMT unmethylation, and mesenchymal‐phenotype gliomas." (PMID 31180187, 2019). "In addition to the side effects, TMZ resistance resulting from abnormal expression of MGMT is also an important factor affecting the treatment of gliomas." (PMID 31814867, 2019). "In conclusion, these studies revealed that chemotherapy may provoke an up-regulation of MGMT expression in gliomas through selection of high MGMT expressing cells during chemotherapy." (PMID 32010632, 2019). "MGMT autoantibody and its protein expression were performed on same series of glioma samples." (PMID 31210005, 2019). "In four of the 30 patients with glioma, the MGMT promoter was methylated." (PMID 31882734, 2019). "The prognostic value of MGMT in glioma is currently being explored." (PMID 32010632, 2019). "Selective survival of glioma cells with high MGMT expression during alkylating agent therapy may change MGMT status in case of recurrence." (PMID 32010632, 2019). "Similarly, the ITSS grades of IDH1-mutated gliomas were much lower than those of Wild-type gliomas (p < 0.001), and the ITSS grades of MGMT-methylated gliomas were much lower than those of MGMT-unmethylated gliomas (p < 0.001)." (PMID 31745161, 2019). "Subsequently, methylation of MGMT promoter was studied in human glioma samples." (PMID 32010632, 2019). "Selective survival of glioma cells with high MGMT expression during alkylating agent therapy may change MGMT status when recurrence." (PMID 32010632, 2019). "Interestingly, an additional complementary molecular scenario was discovered related to another key marker in human glioma that is also used in clinical practice: the DNA repair enzyme MGMT." (PMID 31428936, 2019). "Recently, a cogent study demonstrated that the extent of MGMT methylation is a predictive marker for progression-free survival (PFS) of glioma patients harboring IDH mutations with TMZ treatment but not radiotherapy." (PMID 31652645, 2019). "For example, DNA repair factors other than MGMT might be highly expressed in glioma stem-like cells." (PMID 31629402, 2019). "Approximately 40% of cancer types, including glioma, exhibit MGMT promoter methylation." (PMID 30542120, 2019). "In high-grade gliomas, epigenetic silencing of MGMT by promoter methylation enhances the sensitivity of tumor cells to alkylating drugs such as temozolomide or nitrosoureas and is, therefore, considered a predictive marker for the clinical response to alkylating chemotherapy." (PMID 31362435, 2019). "We also followed up 10 glioma patients sera (5 seropositive patients and 5 seronegative patients of preoperative) autoantibody levels during postoperative 30 days and the tumor recurrence to validate the changing of anti‐MGMT‐02 peptide autoantibody level." (PMID 31210005, 2019). "Methylation of MGMT promoter is a key predictor of whether alkylating agents can effectively control glioma cells." (PMID 32010632, 2019). "Consistent with our hypothesis, olanzapine did have an inhibitory effect on MGMT in a dose and time‐dependent manner in T98 glioma cells." (PMID 30955240, 2019). "The MGMT promoter has proven to be a strong prognostic biomarker in glioma." (PMID 31426864, 2019). "First, glioma cell models were grouped for MGMT expression levels." (PMID 29486795, 2018).